FGF2 (fibroblast growth factor 2)
Diseases named in the same sentence as FGF2 in open-access papers (continued):
Sharing a sentence is not in itself a finding about the gene and the disease.
cancer (continued). "Recruitment and activation of peritumoral fibroblasts are mediated by growth factors secreted by cancer epithelial and by several TME cell types, such as transforming growth factor-β (TGF-β), platelets-derived growth factor (PDGF) and fibroblast growth factor-2 (FGF-2)." (PMID 32847144, 2020). "Besides active angiogenesis and increased growth kinetics in tumors exhibiting the activation of FGF-2/FGFR autocrine and/or paracrine loops, activated FGF-signaling was shown as a potent regulator of migration and invasion of cancer cells via diverse molecular mechanisms." (PMID 32599808, 2020). "Exosomal miRNAs from cancer cells elicit a parenchymal signaling response at the receptor site and effectively inducing fibroblast activation, such as α-smooth muscle actin (α-SMA), fibroblast growth factor 2 (FGF2) and fibroblast activating protein (FAP) expression." (PMID 32299469, 2020). "Therefore, the inhibition of FGF2, FGFR3, and FGFBP1 may enhance the efficacy of chemotherapy, which is hopeful to make it an irreplaceable sensitizing target for cancer treatment." (PMID 33381388, 2020). "Interestingly, a similar opposing pattern of PROX1:FGF2 expression was observed in all analyzed cancer cell lines, but not cells derived from normal thyroid." (PMID 31717665, 2019). "Importantly, at these concentrations, the inactivation dynamics of ERK1/2 phosphorylation were similar between FGF2-wt and FGF2-STABs, with no signs of abnormally slow signal decay, which would indicate cancer-like dynamics." (PMID 31921844, 2019). "Interestingly, a subset of identified cancer biomarkers (TNFα, sFasL, TRAIL, prolactin, FGF2, SCF, OPN), which were identified in the high diversity/inflammation cluster, were also correlated with Lactobacillus abundance, vaginal pH and genital inflammation and were elevated in the ICC group." (PMID 31089160, 2019). "Therefore, TGF β and FGF2 reciprocally collaborate and may regulate the EMT in the cancer microenvironment and in LECs during PCO development." (PMID 30304871, 2018). "Moreover, the EMT-induced cells treated with FGF2 and TGF β promoted cancer cell invasion." (PMID 30304871, 2018). "In conclusion, we showed non-mitogenic FGF2 maintains the ability for acute cardioprotection from Dox cardiomyocyte toxicity while lacking characteristics that are undesirable in a cancer environment, such as the potential for CK2 activation and upregulation of HO-1." (PMID 30159756, 2018). "Among various factors, PDAC cells secrete Transforming growth factor beta-1 (TGF-β1), Fibroblast growth factor-2 (FGF2), sonic hedgehog (SHH) and platelet-derived growth factor (PDGF) that drive fibroblast proliferation and ECM deposition, which in turn, profoundly affect the cancer cell behavior." (PMID 30108679, 2018). "In NPC for example, LMP1 preserves the cancer stemness of NPC cells by activating the PI3K/AKT pathway; LMP1 critically mediates transformation of nasopharyngeal epithelial cells and facilitates FGF2/FGFR1 signaling activation in the EBV-driven pathogenesis of NPC." (PMID 28009988, 2017). "The recruitment of CAF is induced by diverse cytokines that secreted by cancer cells and other stromal cells, including transforming growth factor-β (TGFβ), epidermal growth factor (EGF), platelet-derived growth factor (PDGF) and fibroblast growth factor 2 (FGF2), CXCL12 and so on30." (PMID 27922075, 2016). "However, FGF2/FGFR signaling in cancer cells is dysregulated, which may contribute to the pathogenesis of many types of cancer." (PMID 27007053, 2016). "Initial experiments exploring FGF2 expression in PDAC described FGF2 apparent in the nuclei of many cancer cells but not in normal pancreatic tissue, suggesting intranuclear FGF2 may be important in this cancer." (PMID 24503018, 2014).
cancer (continued). "Moreover, fibrinogen may produce signals to upregulate the expression of growth factors, such as fibroblast growth factor-2 (FGF-2), vascular endothelial growth factor (VEGF) and platelet-derived growth factor (PDGF), thus promoting malignant tumor cell proliferation and angiogenesis." (PMID 34234871, 2021). "However, the mutual regulation of PROX1 and FGF2 was never investigated in human cancer." (PMID 31717665, 2019). "Notably, these cancer biomarkers functionally comprised of several cytokines (IL-6, MIF, TGF-α, TNFα), apoptosis-related proteins (sFas, sFasL, TRAIL), growth and angiogenic factors (FGF2, HGF, SCF, VEGF), hormones (leptin, prolactin) and other biomarkers (AFP, OPN), but not carcinoma antigens." (PMID 31089160, 2019). "We believe that K119E/R120E and K125E of FGF2 may not induce such mutations in FGFR because the FGF2 mutants bind to FGFR exactly the same way as WT FGF2 and block binding of FGF2 (and other members of the FGF family) to FGFR would not benefit cancer cells." (PMID 28302677, 2017). "Therefore, the levels of serum FGF2 may have prognostic significance in these cancers, and quantification of FGF2 may provide an indirect, non-invasive way to monitor patients with high risk of relapse from solid and hematological tumors." (PMID 27007053, 2016). "Here we first identified SFO as an inducer of EndoMT in the presence of serum and FGF-2 to mimic the in vivo condition, to determine whether SFO could provide a useful chemical tool to study the molecular mechanisms of the EndoMT for therapeutics for the treatment of cancer and fibrosis disease." (PMID 24905361, 2014). "During the EMT process, TGF-β induces the switch of the FGFR isoform of the epithelial cells, which typically do not bind FGF-2, to a sensitive isoform that binds FGF-2 and promotes cancer progression." (PMID 38672507, 2024). "Leveraging the single‐cell resolution of our data, we split cancer cells into FGF2 receptor (FGFR2) positive and negative cells and confirmed that differences observed in FGF2 expression were not due to the library size of the cells." (PMID 37691350, 2023). "To further validate the source of FGF-2 production in the TME, we applied a negative selection strategy to isolate NPC cancer cells without knowing cancer cell surface marker expression." (PMID 35439170, 2022). "Further even though the cancer cell lines used in this study variably expressed FGFR1-4, neither BGJ398 nor recombinant FGF2 in tissue culture altered the best described downstream mediators of FGFR signalling, pERK and pAKT." (PMID 32792542, 2020). "BMPs are thought to induce endothelial mesenchymal transformation (EMT) in cancer cells through SMAD and non-SMAD signaling pathways, while fibroblast growth factor-2 (FGF-2) has been revealed to mediated EMT in corneal endothelial cells." (PMID 29254156, 2017). "Exposure of SW620 or HT29 to exogenous FGF-2, EGF and TGFβ, three cytokines known to induce cancer cell motility, failed to induce elongation and migration." (PMID 25973543, 2015). "In specifically blocking signaling of FGF2/HS complexes through FGFR1, IMB-R1 selectively affects cancer cell survival and exhibits reduced non-specific toxicity compared to chemical pathway inhibitors." (PMID 26201468, 2015). "Dysregulation of miR-133a-3p may also have an accumulative harming effect that may lead to either one or both of cancer and non-cancerous conditions (target genes IL6, and FGF2)." (PMID 34440025, 2021).
cancer (continued). "Active MCs contributed to aggravate inflammation reaction and induced colitis-related cancer by releasing the classical pro-angiogenic and pro-inflammatory factors including VEGF, FGF-2, PDGF, and IL-6, and nonclassical pro-angiogenic factors proteases including tryptase and chymase." (PMID 32209121, 2020). "Moreover, knock-down of FGFR1 resulted in a significant reduction of FGF2 (HMW) in PSCs, but not in cancer cells." (PMID 24503018, 2014). "Furthermore, in patient samples, there was positive correlation of nuclear FGF2 and FGFR1 in myo-fibroblasts, but not in cancer cells." (PMID 24503018, 2014). "Furthermore, we confirmed in 2D culture that nuclear translocation of FGF2 and FGFR1 in stellate cells is regulated by factors secreted specifically by cancer cells rather than normal epithelial cells." (PMID 24503018, 2014). "Furthermore, since FGF2 is secreted by PSCs but not cancer cells, it may fuel an FGFR1 autocrine signalling loop in these cells, stimulating nuclear localisation of FGFR1 and FGF2." (PMID 24503018, 2014).
infection (87 papers, 2010 to 2025). The state of being infected such as from the introduction of a foreign agent such as serum, vaccine, antigenic substance or organism. "Meanwhile, infection with the Delta variant resulted in significant upregulation of the fibroblast growth factor 2 (FGF-2) and VEGF-A, with concentrations of 691.40 and 1,044.00 pg/mL, respectively." (PMID 38568894, 2024). "In addition to pro- and anti-inflammatory cytokines, Delta variant infection increased levels of growth factors FGF-2 and VEGF-A." (PMID 38568894, 2024). "Several reports in the literature show FGF2 level association with infection by ZIKV." (PMID 35714598, 2022). "Our results further suggest an identical pattern of alterations in the expression of these miRNAs and FGF2/FGFR1 in the lungs as a target organ system in a murine model of infection and the potential utility of these miRNAs as diagnostic biomarkers of rickettsial diseases." (PMID 30513762, 2018). "Likewise, total FGF2 (secreted and cell associated; measured by ELISA assay) increased throughout infection." (PMID 21998584, 2011). "In the case of the stainless-steel screw, FGF-2 may have caused tissue to fill the gap between the coating but may not provide a firm adherence between the tissue and the stainless-steel screw, from which infection may have occurred." (PMID 39336460, 2024). "CD55 (complement accelerating factor) and FGF2 (fibroblast growth factor 2) were two genes whose increased expression correlated with viral RNA levels both before and after infection." (PMID 40725231, 2025). "The effect of Omicron BA.1 infection on sprouting angiogenesis was found to be superimposable to that observed upon FGF-2 treatment, representing the positive control." (PMID 40248367, 2025). "The staged release of cefepime and FGF-2 mirrors the findings of Boateng and Catanzano, who reported that multifunctional dressings improve healing outcomes by addressing both infection and regeneration in a coordinated manner." (PMID 39335635, 2024). "The first stage, composed of alginate, AgNPs, and cefepime, targets infection, while the second stage incorporates AgNPs and FGF-2 to support tissue regeneration." (PMID 39335635, 2024). "Our findings suggest that this is also true for community-acquired infections as the subjects who cleared infection had significantly higher levels of IL-1, IL-6, FGF2, and IFN-gamma." (PMID 37973814, 2023). "TNF (degree = 11), CXCL2 (degree = 8), CSF3 (degree = 5), HIST2H2BE (degree = 11) and FGF2 (degree = 10) family proteins were activated and had a strong interaction, indicating that cells had a strong inflammatory response after infection." (PMID 34632719, 2021). "At 4 h, FGF-2 expression was significantly upregulated in pH1N1-alone infection (p = 0.0052) and also at 12 h and 24 h." (PMID 33202895, 2020). "Two rabbits from the FGF‐2 group died 5 days after surgery from postoperative infection, and two rabbits from the vector group died of diarrhoea 12 days after surgery." (PMID 31755222, 2020). "Significant upregulation of FGF-2, a member of the fibroblast growth factor family, was also observed in infection with pH1N1-alone and in pH1N1-MRSA coinfections." (PMID 33202895, 2020). "The other treatment groups were infection + fluconazole (0.5 mg/kg) treatment for seven days or infection + a combination of fluconazole and FGF-2." (PMID 30841504, 2019). "Depending upon the time point and strain of ZIKV used for infection, there was up to 65-fold more FGF2 secreted from ZIKV-infected Sertoli cells." (PMID 29615760, 2018). "Again, R. conorii infection dramatically downregulated both miRNAs in these tissue-specific ECs as early as 30 min post-infection in correlation with higher FGF2/FGFR1 expression." (PMID 30513762, 2018). "The healing outcome of EGF, FGF-2, ofloxacin drops, and observation groups after eliminating infection ear." (PMID 28746231, 2017).
infection (continued). "The infection rates differed significantly among the 4 groups; the EGF and FGF-2 groups had higher rates of otorrhoea, and the infection rate in the ofloxacin drops group was lower." (PMID 28746231, 2017). "Rapid and more-sustained elevations in IL-1ra, MIP-1α, IL-5, IL-10 and IL-17 levels were followed by IL-1β, IL-2, IL-7, IL-9, IL-12, IL-15, IFN-α2, MIP-1β, FGF-2 and GM-CSF at over 2 months post-infection, and accompanied by the recovery of CD4+ cells." (PMID 27830756, 2016). "The FGF-2-apatite composite layer formed at 37 °C reduced the pin tract infection rate and increased the fixation strength at the bone-pin interface." (PMID 24918287, 2014). "The results of this study suggest that the chemistry of the calcium phosphate matrix that embeds FGF-2, in addition to FGF-2 content and activity, has a significant impact on composite infection resistance and fixation strength." (PMID 24918287, 2014). "The resulting FGF-2-apatite composite layer on the Ti pin reduced pin tract infection rate in the same animal model." (PMID 24351822, 2013). "Together, these results suggest that C. trachomatis infection stimulates production and release of FGF2, which can then be co-opted by C. trachomatis to facilitate additional rounds of infection and bacterial spread." (PMID 21998584, 2011). "Nonetheless, these results show that FGF2 is sufficient to enhance C. trachomatis binding in an HSPG-sensitive manner and that FGF2-mediated C. trachomatis binding leads to productive infection." (PMID 21998584, 2011). "In summary, our results demonstrate that C. trachomatis co-opts FGF2 to enhance infection and bacterial spread." (PMID 21998584, 2011). "Conversely, the level of fibroblast growth factor-2 (FGF-2), a cytokine involved in vascular repair, was found to be low during the early phase of infection and tended to increase only later particularly in patients with prolonged illness or more severe lung damage." (PMID 40872813, 2025). "Research indicates that approximately half of patients with community-acquired acute hepatitis C can spontaneously clear the virus, and significantly higher levels of IL-1β, IL-1RA, IL-6, IFN-γ, and FGF-2 were detected in the serum of patients achieving self-limited infection." (PMID 40934209, 2025). "Additionally, diverse pathologies associated with neurodegenerative diseases, infection, ischemia, and traumatic injury are linked to increased levels of OSM, LIF, GDF-15, and FGF-2." (PMID 39683685, 2024). "BEAS-2B infection with RV-1B, and subsequent conditioned medium transfer to lung fibroblasts, induced fibroblast proliferation that was partly dependent on the availability of FGF2." (PMID 37773065, 2023). "In EAE mice, infection increased the level of FGF-2 and FGF-7 in CSF." (PMID 36836678, 2023). "Patients clearing infection also had higher levels of fibroblast growth factor 2 (FGF2)." (PMID 37973814, 2023). "Our discovery that the administration of recombinant FGF-2 into mice post-infection with C. albicans significantly increased mortality compared to non-FGF-2-treated animals suggests that angiogenesis mediated by FGF-2 enhances the pathogenicity of C. albicans during a disseminated infection." (PMID 30841504, 2019). "Finally, enhanced FGF2 secretion was also observed in persistently infected samples although the levels were much lower than during acute infection." (PMID 29615760, 2018). "The healing outcome of EGF, FGF-2, ofloxacin ear drop, and observation group of infection ear." (PMID 28746231, 2017). "We found that miR-194 significantly downregulated FGF2 expression at 24 h post-infection." (PMID 29163456, 2017). "Although we cannot exclude the potential contribution of parasite arginase in the IGF-1 and FGF-2-mediated effects on macrophages, we found previously that L. donovani arginase contributed little to the overall arginase expression at the site of infection in this model of progressive VL." (PMID 24967908, 2014).